DYRK2 (dual specificity tyrosine phosphorylation regulated kinase 2)
Diseases named in the same sentence as DYRK2 in open-access papers (continued):
Sharing a sentence is not in itself a finding about the gene and the disease.
gastric cancer (3 papers, 2011 to 2023). A primary or metastatic malignant neoplasm involving the stomach. "The role of DYRK2 in gastric cancer has been investigated in patient tissue samples, cell lines, and xenograft mouse models." (PMID 37886981, 2023). "DYRK2 knockout or knockdown gastric cancer cell lines, MKN1 and AGS, showed increased proliferation, whereas a DYRK2-overexpressed gastric cancer cell line, HGC-27, showed decreased proliferation." (PMID 37886981, 2023). "We also discovered long-range epigenetic silencing (LRES) regions in gastric cancer tissue and identified several hypermethylated genes (MDM2, DYRK2, and LYZ) within these regions." (PMID 22133303, 2011). "Low DYRK2 expression, older age, TNM stages (especially later TNM, T, or N stages), and high preoperative carcinoembryonic antigen levels correlate with poor five-year survival rates in patients with gastric cancer." (PMID 37886981, 2023).
hepatocellular carcinoma (3 papers, 2020 to 2023). A malignant tumor that arises from hepatocytes. "Patients with hepatocellular carcinoma (HCC) and low DYRK2 expression have significantly shorter survival times than those with high DYRK2 expression." (PMID 37886981, 2023).
lymphoma (3 papers, 2020 to 2023). A malignant (clonal) proliferation of B- lymphocytes or T- lymphocytes which involves the lymph nodes, bone marrow and/or extranodal sites. "In conjunction with the reduced expression of DYRK2 in tumor samples, DYRK2 depletion promotes the proliferation of cell lines originating from distinct tumor types, including breast, lymphoma, osteosarcoma, CRC and HCC, suggesting that DYRK2 may acts as a brake on proliferation." (PMID 32751160, 2020). "In addition, DYRK2 expression may correlate with the prognosis of patients with lymphoma." (PMID 37886981, 2023).
neuroblastoma (3 papers, 2022 to 2023). Neuroblastoma (NB) is the most common solid, extracranial childhood tumor. "Accordingly, pinoresinol, another plant compound found in the human diet, was also passed to the rats’ offspring, which appears as a feasible DYRK2 inhibitor with potential preventive activity against neuroblastoma." (PMID 37108565, 2023). "Park also reported that an in vitro drug treatment that inhibited neuroblastoma growth involved DYRK2 downregulation." (PMID 36161154, 2022). "All together these data reveal that DYRK2 might promote the survival and growth of neuroblastoma cells." (PMID 36161154, 2022). "A clinical study suggested the role of DYRK2 in tumorigenesis of neuroblastoma." (PMID 35807542, 2022). "Regarding nervous system malignancies, Uhl found DYRK2 and DYRK3 upregulation in neuroblastoma (an aggressive tumor affecting the sympathetic system and/or adrenal glands in early childhood) patients with poor prognoses." (PMID 36161154, 2022). "Besides, treating neuroblastoma cell lines with LDN-192960, a DYRK2 inhibitor, resulted in a high cytotoxic effect suggesting a key role for DYRK2 in the survival of tumoral cells." (PMID 36161154, 2022).
ovarian serous adenocarcinoma (3 papers, 2018 to 2023). An adenocarcinoma that arises from the ovary and is characterized by the presence of malignant epithelial cells that, in well differentiated tumors, resemble the epithelium of the fallopian tube or, in poorly differentiated tumors, show anaplastic features and marked nuclear atypia. "In contrast, in ovarian serous adenocarcinoma, diminished DYRK2 expression is associated with a poorer prognosis." (PMID 38139175, 2023).
prostate carcinoma (3 papers, 2022 to 2025). A carcinoma that arises from epithelial cells of the prostate gland. "One study reported that prostate cancer tissue samples have markedly lower DYRK2 expression levels than normal tissue samples." (PMID 37886981, 2023). "The role of DYRK2 in prostate cancer has been investigated in tissue samples, cell lines, and xenograft mouse models." (PMID 37886981, 2023). "Here, the authors identify DYRK2 as a target for prostate cancer with a role in invasion and they discover a specific DYRK2 inhibitor that has good pharmacokinetics and efficacy in vivo." (PMID 35614066, 2022). "To investigate which signaling pathways are responsible for the anti-prostate cancer function of DYRK2 inhibitors, we performed transcriptome-wide RNA-sequencing analysis of DYRK2 KD- and YK-2-69- treated human DU145 and 22Rv1 cells as well as control cells." (PMID 35614066, 2022). "Another study reported high DYRK2 expression in tissue samples from patients with prostate cancer." (PMID 37886981, 2023). "The kinase DYRK2 is a known oncogene but its role in prostate cancer is unexplored." (PMID 35614066, 2022). "However, DYRK2 Inhibitor has been developed for the treatment of prostate cancer." (PMID 40190550, 2025).
viral infection (3 papers, 2015 to 2022). "In the response of cells to viral infections, the dual-specificity tyrosine-(Y)-phosphorylation-regulated kinase 2 (DYRK2) phosphorylates TBK1 at S527, leading to polyubiquitination and degradation of the protein." (PMID 28408866, 2017). "Although all DYRKs have been involved in different diseases, including congenital malformations, cancer, and virus infection, different lines of evidence suggest that DYRK1A and DYRK2 are the most relevant forms for human disease." (PMID 36161154, 2022). "Third, the interaction between DYRK2 and TBK1 was the strongest at twelve hours after viral infection under physiological conditions; the interaction subsequently gradually disappeared." (PMID 26407194, 2015).
Alzheimer disease (2 papers, 2022 to 2026). A progressive, neurodegenerative disease characterized by loss of function and death of nerve cells in several areas of the brain leading to loss of cognitive function such as memory and language. "This study introduces PhysDual-GCN, a physics-informed graph neural network designed to approximate docking-derived binding affinity scores for DYRK2, an understudied yet biologically relevant target in Alzheimer's disease (AD)." (PMID 41673049, 2026).
colon cancer (2 papers, 2016 to 2021). "DYRK2 expression was also downregulated transcriptionally by DNA methyltransferase 1 in colon cancer." (PMID 33376136, 2021). "This study also confirmed that decreased expression of DYRK2 happened in rectal cancer more often than in colon cancer." (PMID 27532268, 2016). "Our current study presented the first piece of evidence that DYRK2 was down regulated in colon cancer at both transcriptional and translational levels." (PMID 27532268, 2016). "Interestingly, our current study observed more cases of decreased expression of DYRK2 in rectal cancer than in colon cancer (P = 0.023)." (PMID 27532268, 2016).
esophageal cancer (2 papers, 2022 to 2023). A primary or metastatic malignant neoplasm involving the esophagus. "The correlation between the expression of DYRK2 and the pathological stages of cancers, including ESCA(Esophageal carcinoma),HNSC(Head and Neck squamous cell carcinoma) and LIHC(Liver hepatocellular carcinoma) were analyzed by the GEPIA2 tool (all P < 0.05)." (PMID 36104345, 2022). "Furthermore, no cancer studies have reported that DYRK2 functions only as an oncogene, with the exception of esophageal cancer." (PMID 37886981, 2023). "In TCGA, high expression of DYRK2 predicted poorer overall survival in KICH (Kidney Chromophobe) (P = 0.0083), LAML (Acute Myeloid Leukemia) (P = 0.039), UVM (Uveal Melanoma) (P = 0.039), MESO (Mesothelioma) (P = 0.026) and ESCA(Esophageal carcinoma) (P = 0.048)." (PMID 36104345, 2022).
liver cancer (2 papers, 2021 to 2023). An epithelial or non-epithelial malignant neoplasm that arises from the liver. "The role of DYRK2 in liver cancer has been investigated in patient tissue samples, cell lines, xenograft mouse models, and genetically modified mouse models." (PMID 37886981, 2023). "DYRK2 expression is decreased in liver cancer cells and is strongly related to the pathological grade of patients with liver cancer." (PMID 37886981, 2023). "Moreover, DYRK2 depletion promotes liver cancer cell proliferation and increases oxaliplatin resistance." (PMID 37886981, 2023). "Therefore, DYRK2 expression may serve as a predictor of liver cancer." (PMID 37886981, 2023).
malignant melanoma (2 papers, 2020 to 2022). "Moreover, a significant DYRK2 overexpression in DYRK2-amplified tumors was also observed in HNSCC, ovary (OV), melanoma (SKCM) and sarcoma (SARC)." (PMID 32751160, 2020).
non-small cell lung carcinoma (2 papers, 2015 to 2016). A group of at least three distinct histological types of lung cancer, including non-small cell squamous cell carcinoma, adenocarcinoma, and large cell carcinoma. "For example, overexpression of DYRK2 predicts a better survival in human non-small cell lung cancer." (PMID 27532268, 2016). "Moreover, patients with DYRK2-positive tumors in recurrent non-small cell lung cancer has substantially benefited from chemotherapy as compared with those with DYRK2-negative tumors." (PMID 27532268, 2016).
rectal adenocarcinoma (2 papers, 2016 to 2022). "Specifically, In 65 pairs of normal rectum and primary rectal adenocarcinoma, the level of DYRK2 is lower in cancer tissue compared to paired adjacent normal tissues significantly." (PMID 27532268, 2016).
adenovirus infection (1 paper, 2020). "(D) Expression of Gli1 and Ptch1 in Dyrk2-/- MEFs overexpressing human DYRK2 or DYRK2-K251R (kinase dead) constructs via adenovirus infection was measured by qPCR." (PMID 32758357, 2020).
Adrenocortical carcinoma (1 paper, 2022). "Meanwhile, disease-free survival (DFS) data showed that high expression of DYRK2 suggested poor prognosis in TCGA cases in ACC (Adrenocortical carcinoma) (P = 0.025), KICH(Kidney Chromophobe) (P = 0.027) and PRAD (Prostate adenocarcinoma) (P = 0.015)." (PMID 36104345, 2022).
anal atresia (1 paper, 2021). "At E18.5, all Dyrk2−/− embryos displayed multiple defects, including the omphalocele phenotype, craniofacial development, short limb, and anal atresia, as well as an open eyelid phenotype at times." (PMID 34671097, 2021).
astrocytoma (1 paper, 2023). "Clustered cell populations in astrocytoma also exhibited a modest overlap of DYRK2 and HSF1." (PMID 36622366, 2023).
ataxia telangiectasia (1 paper, 2013). Ataxia-telangiectasia is the association of severe combined immunodeficiency (affecting mainly the humoral immune response) with progressive cerebellar ataxia. "In addition, ataxia telangiectasia mutated was shown to phosphorylate nuclear DYRK2 upon DNA damage, which appeared to enable DYRK2 to protect itself from degradation that occurs due to its association with MDM2 under normal conditions." (PMID 23665168, 2013).
autoimmune disease (1 paper, 2022). A disorder resulting from loss of function or tissue destruction of an organ or multiple organs, arising from humoral or cellular immune responses of the individual to their own tissue constituents. "The DEMs targeting DYRK2 were miR-181a-5p, miR-326, and miR-874-3p (positively correlated to islet autoantibodies) and miR-148b-3p, all previously related to T1D and/or autoimmune diseases." (PMID 35903753, 2022).
bladder cancer (1 paper, 2015). "The present study therefore examined the association between DYRK2 expression and efficacy of neoadjuvant chemotherapy in clinical practice for patients with T1 high-grade or T2 bladder cancer." (PMID 26087959, 2015). "High levels of DYRK2 expression was associated with increased disease-specific survival time in T1 high-grade and T2 bladder cancer patients treated with neoadjuvant chemotherapy." (PMID 26087959, 2015). "The present study revealed a significant association between DYRK2 expression and efficacy of neoadjuvant chemotherapy for T1 high-grade and T2 bladder cancer patients." (PMID 26087959, 2015). "The results of the present study indicate that DYRK2 can help identify patients with T1 high-grade and T2 bladder cancer that will respond to neoadjuvant chemotherapy." (PMID 26087959, 2015). "Immunohistochemical analysis was used to determine expression of DYRK2 in bladder cancer specimens obtained by transurethral resection before chemotherapy." (PMID 26087959, 2015). "Although the sample size of this study was small, our results indicate that DYRK2 might represent a new molecular marker for predicting the efficacy of neoadjuvant chemotherapy in T1 high-grade and T2 bladder cancer." (PMID 26087959, 2015). "DYRK2 expression level may predict the efficacy of neoadjuvant chemotherapy for T1 high-grade and T2 bladder cancer." (PMID 26087959, 2015). "Thus, Use of ERCC1, MDR1, BRCA1, and Snail in combination with DYRK2 may further improve the accuracy of predicting survival in bladder cancer patients treated with neoadjuvant chemotherapy." (PMID 26087959, 2015). "One limitation of the present study is that we have not shown a direct role of DYRK2 in bladder cancer." (PMID 26087959, 2015).
bladder tumor (1 paper, 2015). "DYRK2 was localized in the cytoplasm of bladder tumor cells." (PMID 26087959, 2015).
brain tumors (1 paper, 2023).
breast tumor (1 paper, 2020). "In any case, the DYRK2-associated stratification of breast tumors should be properly studied before designing any DYRK2-targeting therapeutic approach." (PMID 32751160, 2020). "Indeed, DYRK2 levels negatively correlated with c-Jun/Myc levels in breast tumor tissues." (PMID 32751160, 2020).
cardiac hypertrophy (1 paper, 2013). "This study is the first to show that the interaction of GSK-3β and its priming kinase DYRK2 is a potent regulatory mechanism of the activity of eIF2B and cardiac hypertrophy in vivo." (PMID 24023715, 2013). "In conclusion with our in vitro findings, the correlation of DYRK2 and phospho-eIF2Bε with conditions of increased protein synthesis are indicative for a physiological role of this regulatory axis in cardiac hypertrophy." (PMID 24023715, 2013). "While the extent of protein expression of DYRK1A, which has recently been identified to be a negative regulator of cardiac hypertrophy, was not changed in our transgenic model, we observed a concomitant upregulation of DYRK2 in animals overexpressing eIF2Bε." (PMID 24023715, 2013).
ciliopathy (1 paper, 2020). A genetic disorder of the cellular cilia or the cilia anchoring structures, the basal bodies, or of ciliary function. "While the present study does not include any evidence to support the relationship between DYRK2 and human disease, our results do suggest a possibility that DYRK2 is involved in human ciliopathy, particularly in regard to skeletal disorders." (PMID 32758357, 2020). "Additionally, DYRK2 is a ciliary protein that is primarily localized at the basal body and the TZ, which contains a growing number of ciliopathy proteins." (PMID 32758357, 2020).
colorectal tumors (1 paper, 2022). "For instance, DYRK2 expression was significantly down-regulated in colorectal tumors whereas CDC25A showed increased expression in comparison with healthy tissue; similarly, DYRK2 expression was higher in kidney tumors than in adjacent normal tissues whereas CDC25A showed the opposite pattern." (PMID 34363019, 2022).
coronary artery disease (1 paper, 2025). "Further, patients with coronary artery disease also present with a significant decrease in miR-187 expression and experimental overexpression through knockdown of its downstream target, DYRK2, improved cardiomyocyte apoptosis in a hypoxia/reoxygenation model of myocardial infarction." (PMID 40027601, 2025).
cyst (1 paper, 2021). A sac-like closed membranous structure that may be empty or contain fluid or amorphous material. "The Dyrk2−/− embryos exhibited lung immaturity, hypoplasia, fusion of the right lung lobes, and a large cyst on the lower left lung." (PMID 34671097, 2021).
epilepsy (1 paper, 2022). A brain disorder characterized by episodes of abnormally increased neuronal discharge resulting in transient episodes of sensory or motor neurological dysfunction, or psychic dysfunction. "DYRK2 has been related to epilepsy, a neurological condition not well understood and characterized by recurrent seizures." (PMID 36161154, 2022).
fibrosis (1 paper, 2021). the formation of excess fibrous connective tissue in an organ or tissue in a reparative or reactive process. "However, cardiomyocyte-derived miR-217- and miR-208-containing exosomes resulted in cardiac dysfunction and worsened cardiac fibrosis via targeting phosphatase and tensin homolog (PTEN) and dual-specificity tyrosine phosphorylation-regulated kinase 2 (Dyrk2) separately." (PMID 34485413, 2021).
Hydrocephalus (1 paper, 2020). Hydrocephalus is an active distension of the ventricular system of the brain resulting from inadequate passage of CSF from its point of production within the cerebral ventricles to its point of absorption into the systemic circulation. "Among these kinases, Dyrk2-/- embryos exhibit similar phenotypes to Ick-deletion mice in vivo such as skeletal defects and cilia morphology, although they do not possess a hydrocephalus defect." (PMID 32758357, 2020).
invasive ductal carcinoma (1 paper, 2023). "We have previously shown that nuclear expressions of DYRK2 and HSF1 correlate in TNBC and quadruple-negative breast cancer (QNBC: ER, PR, HER2, and androgen receptor negative) subtypes of invasive ductal carcinoma patient tumours." (PMID 36622366, 2023).
lymph node metastasis (1 paper, 2022). "DYRK2 expression was found to be correlated with CRC patient lymph node metastasis, liver metastasis, and pathological differentiation in these analyses." (PMID 36577753, 2022). "Relative to patients expressing higher levels of DYRK2, those expressing lower levels of this gene were more likely to exhibit lymph node metastasis, liver metastasis, and worse pathological typing, consistent with DYRK2 downregulation being consistent with a poorer prognosis." (PMID 36577753, 2022).
metastatic colorectal cancer (1 paper, 2023). "DYRK2 mRNA expression in primary or metastatic colorectal cancer is lower than that in normal colon tissue or non-metastatic colorectal cancer." (PMID 37886981, 2023).
non-Hodgkin lymphoma (1 paper, 2023). Distinct from Hodgkin lymphoma both morphologically and biologically, non-Hodgkin lymphoma (NHL) is characterized by the absence of Reed-Sternberg cells, can occur at any age, and usually presents as a localized or generalized lymphadenopathy associated with fever and weight loss. "DYRK2 mRNA and protein levels are reduced in tissue samples from patients with non-Hodgkin’s lymphoma (NHL), and low DYRK2 expression is associated with poor prognosis in patients with NHL." (PMID 37886981, 2023).
omphalocele (1 paper, 2021). Omphalocele is an embryopathy classified in the group of abdominal celosomias and is characterized by a large hernia of the abdominal wall, centered on the umbilical cord, in which the protruding viscera are protected by a sac. "Dyrk2 deficiency affected intestinal villus morphogenesis and proliferation patterns with omphalocele phenotypes." (PMID 34671097, 2021).
oral cancer (1 paper, 2023). "Finally, we used the GSE42743 data set of Gene Expression Omnibus (GEO) to analyze the expression profile of DYRK2 and DYRK3 genes in oral cancer and adjacent normal tissues." (PMID 38139175, 2023).